TFF3 (trefoil factor 3)
Diseases named in the same sentence as TFF3 in open-access papers (continued):
Sharing a sentence is not in itself a finding about the gene and the disease.
prostate carcinoma (25 papers, 2008 to 2025). A carcinoma that arises from epithelial cells of the prostate gland. "Phosphatase and TENsin homolog (PTEN), Erythroblast transformation-specific–related gene (ERG), Serine protease inhibitor Kazal-type 1 (SPINK1), and Trefoil Factor 3 (TFF3) have been identified as important biomarkers for prostate cancer." (PMID 38256434, 2024). "TFF3 shows promise as a biomarker for both subtyping prostate cancer and assessing renal damage in TFF3-positive cases." (PMID 37894380, 2023). "BMMSC-EVs delivered exogenous miRNA-143 to inhibit cell migration and invasion of human prostate cancer by downregulating trefoil factor 3 (TFF3)." (PMID 35915054, 2022). "In prostate cancer, TFF3 silencing induced mitochondria-mediated apoptosis, thus suppressing tumor growth and migration." (PMID 35626334, 2022). "Through their own exosomes, MSCs can deliver overexpressed miR-143 to prostate cancer cells, and this downregulates TFF3 expression, thereby inhibiting the proliferation and invasion of prostate cancer cells and promoting their apoptosis." (PMID 34335792, 2021). "They demonstrated that MSC-derived exosomal miR-143 suppressed proliferation, migration, invasion, and tumor growth and induced apoptosis in prostate cancer cells by targeting trefoil factor 3 (TFF3)." (PMID 31614612, 2019). "We examined the mRNA expression levels of TFF3 in two prostate cancer cell lines (PC-3 and LNCap) and one normal prostate cell line (WPMY-1) by qRT-PCR." (PMID 30139961, 2018). "TFF3 plays an important role in promoting proliferation and migration in many tumor cells such as mammary, prostate carcinoma and HCC cells." (PMID 30424721, 2018). "The overexpression of trefoil factor family 3 (TFF3) is observed in a variety of cancers, including prostate cancer (PCa), and its potential role in carcinogenesis, such as activating the PI3K/AKT pathway, is suggested." (PMID 30139961, 2018). "Hypomethylation of the TFF3 promoter region, resulting in increased TFF3 expression, has been observed in hepatocellular carcinoma, and prostate cancer." (PMID 29100386, 2017). "This is consistent with our previous studies demonstrating that TFF3 stimulates cell proliferation, survival, migration, and 3D and anchorage-independent cell growth of mammary and prostate carcinoma cells." (PMID 28445151, 2017). "Other studies have reported TFF3 as a biomarker for lung cancer, prostate cancer, and cholangiocarcinoma." (PMID 28687783, 2017). "In further support of our data herein, we have previously observed that TFF3 decreases sensitivity towards ionizing radiation in prostate cancer cells." (PMID 28445151, 2017). "For example, our recent study has revealed that TFF3 reduces the sensitivity of prostate carcinoma cells to ionizing radiation." (PMID 28445151, 2017). "Recent studies have reported that TFF3 expression is increased during the development and progression of human cancers, including gastric, breast, colon, and prostate carcinomas among others." (PMID 28445151, 2017). "TFF3 has previously been shown to stimulate survival and proliferation of mammary and prostatic carcinoma cells." (PMID 28445151, 2017). "Abnormally elevated levels of TFF3 have been documented in breast, pancreatic, gastric, and prostate carcinomas." (PMID 18682706, 2008). "Abnormally expressed trefoil factor 3 (TFF3) enhances oncogenesis of prostate cancer cells." (PMID 37067729, 2023). "miR-143 expression is downregulated in prostate cancer cells, and TFF3 expression is upregulated." (PMID 34335792, 2021). "This translates in the post-transcriptional regulation of molecules involved in cell proliferation, migration, invasion, and tumour growth (e.g., MMP-2, MMP-9 and PC3, an anti-proliferative gene), as well as in the regulation of the trefoil factor-3 (TFF3), a promising prostate cancer biomarker." (PMID 32942702, 2020).
prostate carcinoma (continued). "In prostate cancer, TFF3 expression was found to be up-regulated when compared to normal prostate tissue and TFF3 overexpression in PC3 cells was shown to increase proliferation, cell survival, and oncogenicity while reduce ionizing radiation sensitivity in prostate cells." (PMID 33298014, 2020). "TFF3 is reported to be a biomarker for lung cancer, prostate cancer, and cholangiocarcinoma." (PMID 28687783, 2017). "In addition to EC, TFF3 has previously been shown to enhance cell proliferation, survival, oncogenicity, invasion and metastasis of BC, prostate cancer, cervical cancer and hepatocellular carcinoma." (PMID 29100386, 2017). "Notably, other studies have recently reported that serum TFF3 is increased in patients with lung cancer, endometrial cancer, and prostate cancer, and that TFF3 is expressed in the tissue of these cancers." (PMID 24720760, 2014). "Furthermore, in prostate carcinoma cells, TFF3 reduces the sensitivity to ionizing-radiation." (PMID 28070169, 2017). "Background and Objectives: Prognostic biomarkers in prostate cancer (PCa) include PTEN, ERG, SPINK1, and TFF3." (PMID 38256434, 2024). "Overexpression of trefoil factor 3 (TFF3) leads to upregulation of MMP-2 and MMP-9, enhancing prostate cancer cell invasion." (PMID 35765040, 2022). "Six target genes were subjected to protein validation: GPR116, NPY and PLA2G7, three genes over-expressed in ERG+ tissues, and AZGP1, HPGD and TFF3, three genes down-regulated in ERG+ prostate cancer tissues." (PMID 23390522, 2013).
colon carcinoma (20 papers, 2007 to 2024). "Of particular note, a low expression of TFF3 has been proposed to be associated with colon cancer." (PMID 36748835, 2023). "Furthermore, whereas high TFF3 protein levels in colon cancer have been associated with early recurrence after surgery, high TFF3 expression in ovarian cancer is associated with longer recurrence-free survival." (PMID 28930171, 2017). "TFF3, a key oncogene that promoted colon cancer migration and invasion, was also reported in the top genes of this defined cells." (PMID 38880903, 2024). "We performed immunohistochemical staining of TFF3 in 75 paired colon cancer and adjacent mucosa tissues." (PMID 34262017, 2021). "An earlier study in an in vivo rat model showed that high expression of TFF3 conferred more aggressive properties to colon cancer cells including enhanced migration and invasion with increased survival." (PMID 31835445, 2019). "It was reported that highly invasive colon tumours were characterized by decreased expression of TFF3." (PMID 31835445, 2019). "A previous study of the human TFF3 promoter in colon cancer cells had also found that the transcription of TFF3 was precisely controlled by an SP1 binding site, corroborating the results obtained in our experiments." (PMID 29100386, 2017). "TFF3 has been previously reported to increase phosphorylation (Tyr705) of STAT3 in colon carcinoma cell lines." (PMID 25266665, 2014). "Taken together, these data indicated that serum and urine TFF3 levels can be applied as a biomarker for separate gastric and colon cancer detection." (PMID 25031551, 2014). "We also determined serum TFF3 levels in 188 colon cancer patients and 97 healthy controls." (PMID 34262017, 2021). "Besides, exogenous TFF3 protects human colon carcinoma cells and rat intestinal epithelial cells from apoptosis." (PMID 27626280, 2016). "Besides, TFF3 overexpression significantly reduces colon carcinoma cell growth." (PMID 27626280, 2016). "Another SUVmax-related gene, TFF3, which is downregulated in PTCSUV-high tumors, plays a role in angiogenesis and tumorigenesis in breast, stomach, and colon cancers." (PMID 38745021, 2024). "For example, in colon cancer, miR-7 binding to the 3 ′ UTR of TFF3 via the PI3K-AKT signaling pathway to inhibit proliferation and migration." (PMID 36059681, 2022). "Other cancer related genes include the TFF3 gene, which was shown to activate STAT3, (an oncogene) signaling in human colonic cancers and the VEGF receptor FLT1 gene." (PMID 19458770, 2007). "Abnormal expression of trefoil factor 3 (TFF3) in breast, stomach, and colon tumors may be related to the occurrence of tumors, suggesting its role in angiogenesis." (PMID 34567204, 2021).
colorectal cancer (19 papers, 2014 to 2026). A primary or metastatic malignant neoplasm that affects the colon or rectum. "A previous study showed that the expression of MUC2 and TFF3 is decreased in patients with colorectal cancer; therefore, MUC2 and TFF3 are used as diagnostic markers for colorectal cancer." (PMID 40002076, 2025). "The protein encoded by TFF3 is a growth-promoting mucin involved in regulating the progression of several cancers, including gastric, breast, and colorectal cancers." (PMID 40299448, 2025). "In addition, high TFF3 levels are associated with poor survival, recurrence and distant metastasis in colorectal cancer." (PMID 36818673, 2022). "TFF3 levels are significantly elevated in colorectal cancer, where it promotes malignant progression through EMT." (PMID 41551914, 2026). "TFF3 plays an important role in the apoptosis, and cell proliferation along with the promotion of angiogenesis in colorectal cancer." (PMID 39839775, 2024). "With a fold change of 3.5, TFF3 was confirmed to be the most important protein in the pathophysiology of colorectal cancer." (PMID 39839775, 2024). "When TFF3 is overexpressed in colorectal cancer cells, transcription factors such Twist1, Snail, and Vimentin are expressed more often while E-cadherin levels are concurrently decreased." (PMID 39839775, 2024). "AMPC, a small molecule inhibitor of TFF3 has emerged as a potential therapeutic option for colorectal cancer." (PMID 39839775, 2024). "Overexpression of TFF3 in colorectal cancer cells decreases the levels of E-cadherin which results in increased epithelial-mesenchymal transition, enhancing colon cell migration and promoting the formation of secondary tumors, thereby progressing cancer." (PMID 39839775, 2024). "For lymphatic cells, upregulation of PHGR1 and TFF3 was observed, which is essential for the invasion and metastasis of colorectal cancer." (PMID 38778448, 2024). "It was shown that CD147 receptor is essential for TFF3-mediated signaling that regulates colorectal cancer progression." (PMID 37051238, 2023). "In colorectal cancer, TFF3 promotes proliferation, invasion, and migration by enhancing CD147–CD44 interaction to activate transcription 3 (STAT3) and prostaglandin G/H synthase 2 (PTGS2) expression." (PMID 35626334, 2022). "Subsequently, an oral spray of human dimeric recombinant TFF3 was successfully used in a phase II study to treat colorectal cancer patients in order to reduce chemotherapy-induced oral mucositis." (PMID 34830103, 2021). "Pharmacological inhibition of TFF3 dimerization by a synthetic drug was reported to enhance the sensitivity of colorectal carcinoma to chemotherapy." (PMID 34830103, 2021). "Metallothionein-1G overexpression in human colorectal cancer cells HT-29 considerably enhances the induction of Tff3." (PMID 31500117, 2019). "Increased expression of trefoil factor 3 (TFF3) has been reported in colorectal carcinoma (CRC), being correlated with distant metastasis and poor clinical outcomes." (PMID 31835445, 2019). "In accordance with our results, TFF3 has been shown to suppress the growth of colon and colorectal carcinoma cells." (PMID 27626280, 2016). "TFF3 exerts a pro-migratory effect, e.g. on corneal, bronchial, gastric mucosal epithelial, endothelial, and colorectal carcinoma cells as well as oral keratinocytes and rat fibroblasts." (PMID 27626280, 2016). "The urine TFF3 levels in the patients with colorectal cancer were significantly elevated to 5.56 ± 0.696 ng/ml, compared with 1.83 ± 0.162 ng/ml in the group of healthy individuals (P < 0.05)." (PMID 25031551, 2014). "In this study, we found that serum and urine TFF3 levels of the patients with gastric and colorectal cancer were significantly higher that in healthy individuals." (PMID 25031551, 2014).
colorectal cancer (continued). "ROC curve analysis showed that serum TFF3 had 76.6% of positive predictive value, 77.3% sensitivity and 72.5% specificity, with an AUC of 0.819 and optimal cut-off (8.83 ng/ml), when colorectal cancer patients were separated from healthy individuals." (PMID 25031551, 2014). "Serum and urine TFF3 levels were significantly higher in the patients with gastric and colorectal cancer compared with the healthy individuals (P < 0.05)." (PMID 25031551, 2014). "Decreased serum TFF3 levels were significantly correlated with responses to chemotherapy in the colorectal cancer PR group." (PMID 25031551, 2014). "The serum TFF3 levels in the patients with colorectal cancer were 15.86 ± 1.118 ng/ml, and were significantly elevated compared with 7.80 ± 0.233 ng/ml in the group of healthy individuals (P < 0.05)." (PMID 25031551, 2014). "ROC curve analysis showed that urine TFF3 had 75.4% of positive predictive value, 77.2% sensitivity and 72.3% specificity, with an AUC of 0.805 and optimal cut-off (3.01 ng/ml) when colorectal cancer patients were separated from healthy individuals." (PMID 25031551, 2014). "TFF3 is overexpressed in a variety of human malignancies, including gastric and colorectal cancer, and has demonstrated prosurvival, proinvasive and proangiogenic activities." (PMID 25031551, 2014). "Our data have shown that decreased serum TFF3 levels were significantly correlated with responses to chemotherapy in both the gastric and the colorectal cancer PR groups." (PMID 25031551, 2014). "Taken together, the data indicated that the serum level of TFF3 can be applied as a pharamcodynamic marker of responses to chemotherapy in both gastric and colorectal cancer PR patients." (PMID 25031551, 2014). "TFF3, TFF1, SELE, AHCY, LCN2, CEACAM5, and RETN are consistently upregulated across a variety of datasets and analyzes, which supports their crucial roles in the underlying mechanisms of colorectal cancer progression." (PMID 39839775, 2024). "Alternatively, the Cytosponge-TFF3 test could be performed twice in everyone, in a manner analogous to the serial fecal occult blood testing undertaken in some countries as part of a colorectal cancer screening program." (PMID 25634542, 2015). "To investigate whether urine TFF3 can also be used as a biomarker for gastric and colorectal cancer detection, we analyzed urine and serum TFF3 levels at the same time." (PMID 25031551, 2014). "In summary, our data indicated that serum TFF3 can be applied as an effective biomarker for the detection of tumor stages and distant metastasis and as a predictor of responses to chemotherapy in both gastric and colorectal cancer." (PMID 25031551, 2014). "Therefore, we measured the TFF3 protein levels in serum and urine samples from gastric and colorectal cancer patients prior to treatment, including surgery, chemotherapy and radiotherapy, and from healthy individuals." (PMID 25031551, 2014). "Interestingly, urine TFF3 levels in the patients with gastric and colorectal cancer were significantly elevated compared with the levels of the healthy individuals." (PMID 25031551, 2014). "To define whether serum and urine TFF3 levels could be applied as predictors of responses to chemotherapy, we analyzed the relationship between serum and urine TFF3 levels before and two cycles after chemotherapy in patients with advanced gastric and colorectal cancer." (PMID 25031551, 2014). "Age and the number of lymph node metastases were significantly correlated with serum TFF3 levels in colorectal cancer, and decreased serum TFF3 levels were significantly correlated with responses to chemotherapy in both the gastric and the colorectal cancer partial response (PR) groups." (PMID 25031551, 2014). "Thus, our results suggested that serum TFF3 may be a potential useful marker for patients with gastric and colorectal cancer and their metastases." (PMID 25031551, 2014).
colorectal cancer (continued). "Interestingly, ET-743 reduced the expression of WISP1, which has been associated to a more aggressive phenotype of BTC; another down-regulated gene, TFF3, a member of the trefoil factor (TFF) gene family, was demonstrated to be associated with tumor progression in colorectal cancer and in BTC." (PMID 25479910, 2014). "Trefoil factor 3 (TFF3) has been found to promote cell migration and increase proliferation of colorectal cancer cells." (PMID 39839775, 2024). "Seven proteins, TFF3, LCN2, CEACAM5, TFF1, SELE, RETN, and AHCY were found to be upregulated in other databases and also in our UK Biobank where TFF3 and LCN2 were found to be the most significant proteins and were highly expressed in colorectal cancer." (PMID 39839775, 2024). "The GFR of 26 gastric and 29 colorectal cancer patients was assessed, and urine TFF3 levels were significantly negatively correlated with the GFR in both the gastric and the colorectal cancer groups (P < 0.05)." (PMID 25031551, 2014). "Seven proteins namely TFF3, LCN2, CEACAM5, TFF1, SELE, RETN, and AHCY proteins of both phases were found to be upregulated in colorectal cancer in human protein atlas database, also were significant in our UK Biobank dataset and had an essential function in CRC." (PMID 39839775, 2024). "Similarly, it has been demonstrated that the TFF3- and VEGF-stimulated invasion and growth of colorectal cancer cells is dependent on STAT3 activation." (PMID 29100386, 2017). "Transfecting TFF3 into non-aggressive rat colorectal cancer cells not only enhanced their ability to migrate, but also to invade and behave more aggressively." (PMID 27626280, 2016). "However, urine TFF3 levels were significantly negatively correlated with the GFR in both the gastric and the colorectal cancer groups." (PMID 25031551, 2014).